MIR196A1 (microRNA 196a-1)
Synonyms: hsa-mir-196-1; hsa-mir-196a-1; MIRN196-1; MIRN196A1; mir-196a-1
Gene: MicroRNA gene on chromosome 17 (48,632,490 to 48,632,559, reverse strand). Ensembl gene ENSG00000210741.
Gene Ontology:
Biological process: miRNA-mediated post-transcriptional gene silencing
Cellular component: RISC complex
Homologues: Orthologues: chimpanzee ptr-mir-196a-1 (100% identical), macaque mml-mir-196a-1 (100% identical), dog MIR196A1 (97% identical), guinea pig MIR196A1 (96% identical), pig MIR196A1 (96% identical), rat Mir196c (91% identical). Paralogues in human: MIR196A2 (77% identical), MIR196B (63% identical).
Diseases named in the same sentence as MIR196A1 in open-access papers:
MIR196A1 is named in the same sentence as 3 diseases in open-access papers, as found by Europe PMC text mining. Sharing a sentence is not in itself a finding about the gene and the disease. The quoted sentences say what the papers report.
pancreatic cancer (1 paper, 2015). "MIR196A1 has also been identified as having aberrant expression associated with abnormal apoptosis, invasion and proliferation of pancreatic cancer cells." (PMID 26039411, 2015).
cancer (1 paper, 2018). A tumor composed of atypical neoplastic, often pleomorphic cells that invade other tissues. "Aberrant methylation of MIR196A1 has not yet been reported in human cancer." (PMID 29796116, 2018).
MIR196A1 also shares sentences with these, for which no sentence is quoted: lung carcinoma (1 paper).